CTSD (cathepsin D)
Diseases named in the same sentence as CTSD in open-access papers (continued):
Sharing a sentence is not in itself a finding about the gene and the disease.
diabetic cardiomyopathy (4 papers, 2017 to 2023). Diabetic cardiomyopathy is a disorder of the heart muscle in people with diabetes. "In the current study, excessive autophagy causes increased protein levels of ULK1, Beclin1, LC3II, Cathepsin D, and Fyco1 in diabetic cardiomyopathy, indicating the important role of these proteins in different stages of the autophagy process." (PMID 37764807, 2023). "In our study, the expression of LC3II and P62 was increased, whereas the expression of beclin 1, LAMP2, and cathepsin D was inhibited in the myocardium during diabetic cardiomyopathy and in PA-induced NMCMs." (PMID 37658156, 2023).
Granuloma (4 papers, 2010 to 2023). A compact, organized collection of mature mononuclear phagocytes, which may be but is not necessarily accompanied by accessory features such as necrosis. "The presence of severe granulomas was associated with a profile of up-regulation of innate immunity-related genes such as complement factors C1q and C6, mannose binding protein, lysozyme C, C-type lectin receptor, CD209, Cathepsin D, CD63, LECT-2, CC chemokine and metallothionein." (PMID 20507624, 2010). "When compared to granuloma periphery or mucosa, CD68+ cells in the granulomata demonstrated increased gene expression in lysosome or macrophage-related genes such as CTSD, CD68, HEXB, ATP6V0A1, CTSK, LIPA, CD63." (PMID 36302964, 2022).
neuronal ceroid lipofuscinosis type-10 (4 papers, 2019 to 2021). "Biallelic mutations in the CTSD gene cause a severe neurodegenerative LSD known as neuronal ceroid lipofuscinosis 10 (CLN10)." (PMID 33147750, 2020). "CTSD is a key lysosomal protease involved in degradation of alpha-synuclein that is also implicated in the lysosomal storage neurodegenerative disorder Ceroid lipofuscinosis, neuronal, type 10." (PMID 31721001, 2019). "However, patients with inherited CTSD deficiency develop neuronal ceroid-lipofuscinosis type 10, which is characterized by an altered lipid metabolism in the postmitotic neurons." (PMID 33046706, 2020).
non-alcoholic steatohepatitis (4 papers, 2019 to 2024). "Using a hyperlipidemic murine model for non-alcoholic steatohepatitis (NASH), we have previously demonstrated that the lysosomal protease cathepsin D (CTSD) is involved with lipid dysregulation and inflammation." (PMID 31060228, 2019).
osteoporosis (4 papers, 2021 to 2025). A condition of reduced bone mass, with decreased cortical thickness and a decrease in the number and size of the trabeculae of cancellous bone (but normal chemical composition), resulting in increased fracture incidence. "The protein encoded by CTSD maintains cellular protein homeostasis and is regarded as a bone-related biomarker of osteoporosis." (PMID 38633108, 2024). "Molecular docking results indicated that MEHP may influence osteoporosis by interacting with three proteins: CTSD, VCP, and SOAT." (PMID 40969353, 2025). "It will be worthwhile to further study the roles of PTPN6, CTSD, and FOS in other cells or biological processes except osteoclasts, and explore their significance in the occurrence and development of osteoporosis from the perspective of proteomics and protein modification omics." (PMID 35095774, 2021).
preeclampsia (4 papers, 2017 to 2023). Preeclampsia is a hypertensive disorder of pregnancy that is characterized by new-onset hypertension with proteinuria presenting after 20 weeks of gestation, and depending on mild or severe forms may initially present with severe headache, visual disturbances, and hyperreflexia. "Cathepsin C and cathepsin D are risk factors for preeclampsia: a case control study." (PMID 37794357, 2023). "The expression of cathepsin D is significantly lower in serum and placenta of patients in the preeclampsia group than in the third trimester." (PMID 37794357, 2023). "Alternatively, reduced level of cathepsin D was also observed in patients with preeclampsia in a Korean population." (PMID 29375176, 2017). "Few studies have evaluated the impact of cathepsin D in women with preeclampsia." (PMID 31360581, 2019). "This study provides for the first time the changes in serum and placental levels of cathepsin C and cathepsin D in nonpregnant subjects, in all stages of pregnancy, and in patients with preeclampsia at the same time, and explores their significance." (PMID 37794357, 2023).
Stroke (4 papers, 2017 to 2025). Sudden impairment of blood flow to a part of the brain due to occlusion or rupture of an artery to the brain. "We could also explore maintaining CTSD levels through pharmacological interventions to further enhance lysosomal function, protect the brain from stroke-induced cell death, and improve patient outcomes." (PMID 36959587, 2023). "The downregulation of p62 along with fewer expressions of LC3-II, an active form of LC3, and lysosomal enzymes, such as cathepsin D, suggests that autophagy has been activated in CM-treated CNS following stroke due to the elimination of autophagosomes by lysosomes." (PMID 29264419, 2017).
acute myeloid leukemia (3 papers, 2019 to 2025). Acute myeloid leukemia (AML) is a group of neoplasms arising from precursor cells committed to the myeloid cell-line differentiation. "Here we show that CTSD is highly expressed in acute myeloid leukemia (AML) and that high CTSD expression is associated with unfavourable prognosis." (PMID 40796615, 2025). "This study investigates the expression level of cathepsin D (CTSD) in the serum of patients with acute myeloid leukemia (AML) and its clinical significance and evaluates its potential value as a prognostic biomarker for AML." (PMID 41189142, 2025).
amyloid (3 papers, 2008 to 2023). "vCJD neuropathology is characterised by the presence of amyloid plaques, formed from the prion protein, and therefore alterations in the amyloid processing activity of cathepsin D may affect the neuropathogenesis of this disease." (PMID 18426579, 2008). "We did not observe the downregulation of homeostatic genes in AD groups, and while TREM2, CLEC7A and CTSD were indeed overexpressed in the presence of amyloidosis, only TREM2 and CTSD upregulation seemed to be specific of FAAH deletion in pathological conditions." (PMID 34587978, 2021).
cardiac hypertrophy (3 papers, 2020 to 2021). "Yet, a few studies have a contrasting conclusion, they reported that decreased myocardial and serum CTSD levels were relatively lower in SCD with cardiac hypertrophy." (PMID 33964876, 2021). "According to the study of Ricke‐Hoch, pregnant mice with a cardiomyocyte‐restricted deletion of Stat3 display cardiac hypertrophy, lower capillary density and increased cathepsin D activity." (PMID 32529705, 2020). "Therefore, further studies are required to focus on cardiac hypertrophy and SCD, to decipher the precise role of myocardial CTSD in SCH." (PMID 32176724, 2020). "In age-matched groups, cardiac CTSD was significantly downregulated in SCH (p = 0.006) and CTSL was moderately downregulated in CCH (p = 0.021); however, p62, ATPSC, and ASNC were not upregulated in cardiac hypertrophy." (PMID 32176724, 2020).
dyslipidemia (3 papers, 2017 to 2022). "Recent evidence has indicated that cathepsin D (CTSD), a lysosomal enzyme, is a key player in developing hepatic inflammation and dyslipidemia and is a marker for NASH." (PMID 35846147, 2022).
esophageal squamous cell carcinoma (3 papers, 2017 to 2021). Esophageal squamous cell carcinoma (ESCC) is a type of esophageal carcinoma (EC) that can affect any part of the esophagus, but is usually located in the upper or middle third. "Previous studies have demonstrated that cathepsin D exacerbates the invasion of esophageal squamous cell carcinoma, and high cathepsin D expression is associated with poor prognosis." (PMID 28402938, 2017). "Increased expression of cathepsin D (CTSD) is reported to correlate with a poor prognosis in esophageal squamous cell carcinoma and malignant glioma." (PMID 34062746, 2021).
fibrosis (3 papers, 2020 to 2025). the formation of excess fibrous connective tissue in an organ or tissue in a reparative or reactive process. "Cardiomyocyte-expressed LRP6 interacted with cathepsin D (CTSD, a protease) and promoted the degradation of Wnt5a and Wnt11, inhibiting cardiac fibrosis and dysfunction induced by TAC." (PMID 33391533, 2021). "In the present study, CTSD expression was higher in NAFLD patient compared to controls, and a direct correlation was observed between CTSD expression and both NAS and fibrosis." (PMID 32765301, 2020).
Gaucher disease (3 papers, 2012 to 2023). Gaucher disease (GD) is a lysosomal storage disorder encompassing three main forms (types 1, 2 and 3), a fetal form and a variant with cardiac involvement (Gaucher disease - ophthalmoplegia - cardiovascular calcification or Gaucher-like disease). "Upregulation of cathepsin D messenger RNA has been described in the brain of Gaucher disease murine models, whereas in blood from patients with Gaucher disease the activity of various cathepsins is elevated." (PMID 24574503, 2014). "Consistently, over expression of Cathepsin D (CTSD) has been reported in the brain of murine models of several other lysosomal diseases such as Gaucher’s disease, Sandhoff disease, GM1 gangliosidoses, Neimann-Pick A." (PMID 23094108, 2012).
Hyperglycemia (3 papers, 2016 to 2023). An increased concentration of glucose in the blood. "Cathepsin D (CTSD) is known to activate the proapoptotic protein Bid, and is responsible for hyperglycemia-induced cardiomyocyte death." (PMID 36742461, 2023). "In recent years, a large number of studies have found many differentially expressed proteins in the state of hyperglycemia, including bone morphogenetic protein 7, lactoferrin, albumin, cathepsin D, etc.." (PMID 34957219, 2021).
Hypertension (3 papers, 2013 to 2021). The presence of chronic increased pressure in the systemic arterial system. "Given that the other mutants of LRP6 (P1104S) and CTSD (G316R) in hypertension patients were associated with DCM, it is possible that the patients with LRP6 (P1427Q) develop cardiac remodeling or dysfunction in response to stress such as pressure overload or ischemia." (PMID 33391533, 2021). "The study supports the idea that PPCM might be provoked by pathogenic factors including pregnancy-induced hypertension and smoking and it elucidates the potential value of markers such as NT-proBNP, Cathepsin D, ADMA and miRNA-146a as markers for diagnosis and disease monitoring." (PMID 23812247, 2013). "LRP6 (P1104S) and CTSD (G316R) were verified in DCM patients with hypertension from Tongji Hospital (Wuhan, China)." (PMID 33391533, 2021).
liver cancer (3 papers, 2015 to 2025). An epithelial or non-epithelial malignant neoplasm that arises from the liver. "Our results showed significant upregulation of multiple lysosomal proteins in Lal−/− livers, including CTSS and CTSD, which are known to be important mediators in liver fibrosis and liver cancer progression, along with CD68, a well-established macrophage marker." (PMID 37595802, 2023).
liver fibrosis (3 papers, 2023 to 2024). "Cathepsin B (CTSB) and cathepsin D (CTSD) are the two most abundant cathepsins in lysosomes and have been reported to play profibrogenic roles in liver fibrosis; therefore, we hypothesized that they might be the key to the mechanism underlying Prep knockout-induced exacerbated liver fibrosis." (PMID 37394591, 2023). "Therefore, macrophages could be regarded as the main source of these two profibrogenic proteins during liver fibrosis, which in turn indicates that the expression levels of CTSB and CTSD in homogenized liver tissue samples may roughly reflect their levels in hepatic macrophages in vivo." (PMID 37394591, 2023).
lung adenocarcinoma (3 papers, 2006 to 2023). A carcinoma that arises from the lung and is characterized by the presence of malignant glandular epithelial cells. "Large cell lung carcinomas and lung adenocarcinomas displayed predominantly tumor-cell cathepsin D expression and weak stromal expression." (PMID 17183660, 2006).
lymph node metastasis (3 papers, 2016 to 2021). "Further analysis showed that the upregulation of CTSB or CTSD was significantly correlated with lymph node metastasis, advanced clinical stage, recurrence, distant metastasis, and poor prognosis." (PMID 26995190, 2016). "Aberrations in the ubiquitin system also have been reported to be associated with various diseases, including cancer, for example, with elevated expression of Cathepsin D and Ubiquitin C-terminal hydrolase-L1 in tumor cells, the incidence of lymph node metastasis in CRC also has increased." (PMID 32127012, 2020). "Interestingly, among all proteases predicted, the cleavage products related to cathepsin D were notably more abundant in pN+ saliva, suggesting an increased activity in the saliva of patients with OSCC and lymph-node metastasis." (PMID 33578082, 2021).
metastatic cancers (3 papers, 2015 to 2025). A carcinoma which has spread from the original site of growth to another anatomic site. "Of the identified proteins, Progranulin and Cathepsin D showed high secretions in castration-sensitive and castration-resistant cell lines, highlighting their potential as biomarkers that should be further investigated in a metastatic cancer setting." (PMID 40075569, 2025). "Interestingly, the proteolytic inactive proform of cathepsin D was detected in the-cell conditioned medium and has also been reported in other metastatic cancers." (PMID 34439122, 2021).
nasopharyngeal carcinoma (3 papers, 2016 to 2020). A carcinoma arising from the nasopharyngeal epithelium. "High expression of CTSD and CTSB was detected in biopsy tissues from nasopharyngeal carcinoma (NPC)." (PMID 26995190, 2016).
nonalcoholic fatty liver disease (3 papers, 2020 to 2024). "In some studies, Currently, circulating cathepsin D levels in nonalcoholic fatty liver disease were shown to be useful for the assessment of disease severity." (PMID 37280603, 2023). "Highly specific and potent small-molecule inhibitors of CTSD other than Pepstatin A have been developed for the treatment of non-alcoholic fatty liver disease, as well as CTSD targeting by natural products has shown to be beneficial in cancer chemoprevention." (PMID 32326609, 2020). "Notably, CTSD and BAX have been implicated in the onset of nonalcoholic fatty liver disease (NAFLD)." (PMID 39641053, 2024).
oral carcinoma (3 papers, 2016 to 2021). "The relationship between tissue levels of cathepsin D and invasion, progression, and metastasis has been observed for oral carcinoma." (PMID 33578082, 2021). "Here, it is interesting to note that a shift in localization of cathepsin D from the lysosomes to the cells surface can occur, as reported in models of oral carcinoma progression." (PMID 33266503, 2020). "The Kaplan-Meier curve showed that oral cancer patients with higher expression of CTSD had a significantly poor survival in oral cancer patients (p = 0.048)." (PMID 27031837, 2016).
pneumococcal infection (3 papers, 2011 to 2022). Infections with bacteria of the species streptococcus pneumoniae. "Cathepsin D activation was shown to trigger apoptosis during pneumococcal infection in macrophages, while its pharmacological inhibition blocked this process." (PMID 36612268, 2022). "In contrast, we observed that pneumococcal infection enhanced the ubiquitination of Mcl-1 and that cathepsin D inhibition reversed this process." (PMID 21298030, 2011). "The delayed process of cell death we have observed following pneumococcal infection is differentiation-dependent, commensurate with the accumulation of lysosomes and of cathepsin D in differentiated macrophages." (PMID 21298030, 2011). "In this study, we demonstrate that LMP and cathepsin D activation trigger macrophage apoptosis via Mcl-1 downregulation during pneumococcal infection." (PMID 21298030, 2011). "Pharmacological inhibition or knockout of cathepsin D during pneumococcal infection blocked macrophage apoptosis." (PMID 21298030, 2011). "A functional assay, based on the proteolytic processing of a fluorogenic cathepsin D substrate, confirmed that pneumococcal infection of macrophages resulted in enhanced cathepsin D activity as early as 8 h post-infection, provided that the pneumococci expressed the toxin pneumolysin." (PMID 21298030, 2011). "We have previously shown cathepsin D activates MOMP, caspase 3 activation, and nuclear fragmentation in macrophages, all characteristics of apoptosis, during pneumococcal infection and once again confirm here that the PCD resembles apoptosis." (PMID 25293758, 2014). "The key findings of cathepsin D activation, LLA and reduced apoptosis (dissipation of ΔΨm and nuclear fragmentation) with pepstatin A treatment, following pneumococcal infection, were replicated in monocyte-derived macrophages (MDM)." (PMID 21298030, 2011). "We confirmed that caspase inhibition, which reduces macrophage apoptosis, but does not alter cathepsin D activation after pneumococcal infection, reduced bacterial killing in differentiated THP-1 cells." (PMID 21298030, 2011). "We found that pneumococcal infection activated cathepsin D, while phagocytosis of Staph. aureus failed to do so." (PMID 21298030, 2011). "We evaluated several cathepsins but observed that cathepsin D was the major mediator of macrophage apoptosis induced during pneumococcal infection, though not the only factor as evidenced by the fact that absence of cathepsin D activation did not completely abolish apoptosis." (PMID 21298030, 2011).
renal carcinoma (3 papers, 2009 to 2022). A carcinoma arising from the epithelium of the renal parenchyma or the renal pelvis. "We propose that the association identified here between pVHL30 and CTSD may play a role in renal cancer progression." (PMID 35205757, 2022).
serous ovarian carcinoma (3 papers, 2013 to 2021). "A significant overexpression of CTSD in the omental lesion of serous ovarian carcinoma was observed, and it is believed to be associated with poor disease-specific survival." (PMID 32244796, 2020). "Furthermore, many immunohistochemical results showed that the enhanced expression of CTSD encoded protein was an indicator of the malignant degree of serous ovarian cancer." (PMID 34873574, 2021). "It has been reported that CTSD is an indicator of malignancy in serous ovarian carcinoma, and it is expressed more highly in serous ovarian carcinoma than in benign serous ovarian tumor." (PMID 23431385, 2013). "Enhanced CTSD expression is considered an indicator of malignancy in serous ovarian cancer." (PMID 32244796, 2020).
steatosis (3 papers, 2019 to 2024). Increased lipid within the cytoplasm of cells. "While we successfully demonstrated the importance of extracellular CTSD activity in steatosis, the underlying mechanism of extracellular CTSD action compared to intracellular CTSD inhibition in NASH-associated hepatic inflammation was never investigated." (PMID 34335574, 2021). "We have previously demonstrated that specific inhibition of the extracellular CTSD leads to improved metabolic features in Sprague-Dawley rats with steatosis." (PMID 34335574, 2021). "Conversely, the mean absolute levels of plasma CTSD were highest at the lowest NAS steatosis score and remained rather stable when NAS steatosis scores increased." (PMID 39263329, 2024). "Upon administration of the extracellular CTSD inhibitor, we observed that HFD-fed rats showed a significant reduction in plasma insulin levels and improvement of steatosis, two important characteristics of diet-induced NAFLD." (PMID 31060228, 2019).